KLF14 (KLF transcription factor 14)
Synonyms: BTEB5
Tractability: PROTAC: ubiquitination databases record sites on it.
Gene: Protein-coding gene on chromosome 7 (130,730,697 to 130,734,207, reverse strand). Ensembl gene ENSG00000266265.
Subcellular location: Nucleus
Gene Ontology:
Molecular function: sequence-specific DNA binding; sequence-specific double-stranded DNA binding; DNA-binding transcription factor activity, RNA polymerase II-specific; RNA polymerase II cis-regulatory region sequence-specific DNA binding; chromatin binding
Biological process: positive regulation of transcription by RNA polymerase II; regulation of transcription by RNA polymerase II
Cellular component: chromatin; nucleus
Genetic constraint (gnomAD): Loss-of-function variants: 13 observed, 11.6 expected, observed/expected ratio (o/e) 1.12, 90% interval 0.73 to 1.73. The synonymous counts are far from expectation, so gnomAD's model fits this gene poorly and the ratio says little. Missense variants: 571 observed, 411.27 expected, observed/expected ratio (o/e) 1.39, 90% interval 1.3 to 1.49. Synonymous variants: 276 observed, 197.11 expected, observed/expected ratio (o/e) 1.4, 90% interval 1.27 to 1.55.
Homologues: Orthologues: chimpanzee KLF14 (99% identical), macaque KLF14 (96% identical), dog KLF14 (82% identical), rabbit KLF14 (82% identical), pig KLF14 (81% identical), mouse Klf14 (66% identical), rat Klf14 (66% identical), zebrafish klf13 (33% identical), zebrafish zgc:153115 (32% identical), zebrafish klf5l (20% identical), zebrafish sp5l (20% identical), Drosophila melanogaster dar1 (20% identical), and 11 more. Paralogues in human: KLF16 (43% identical), KLF13 (36% identical), KLF9 (30% identical), KLF11 (29% identical), KLF10 (26% identical), SP9 (24% identical), SP8 (24% identical), SP7 (23% identical), SP5 (22% identical), KLF12 (21% identical), SP6 (21% identical), KLF5 (20% identical), and 10 more.
Diseases named in the same sentence as KLF14 in open-access papers:
KLF14 is named in the same sentence as 67 diseases in open-access papers, as found by Europe PMC text mining. Sharing a sentence is not in itself a finding about the gene and the disease. The quoted sentences say what the papers report.
type 2 diabetes (18 papers, 2011 to 2025). "The type 2 diabetes risk-increasing maternal allele C in the KLF14 variant increased triglyceride levels while the T allele decreased them." (PMID 40175764, 2025). "According to the Diabetes Genetics Replication and Meta-analysis (DIAGRAM) organization, the C allele of KLF14 rs4731702 is associated with an increased risk of type 2 diabetes mellitus." (PMID 37351102, 2023). "Some GWAS results also disclosed that genetic variants surrounding the KLF14 gene are closely linked to type 2 diabetes, HDL-C levels, metabolic syndrome, HbA1C, and atherosclerosis." (PMID 35238325, 2022). "Mapping studies have identified two SNPs (rs4731702, rs972283) upstream of KLF14 associated with type II diabetes and cholesterol levels." (PMID 35356864, 2022). "KLF14 is associated with insulin resistance, dyslipidaemia, type 2 diabetes and a female-specific shift of body fat from gynoid to abdominal stores, in agreement with the hip-specific association in women found in our study." (PMID 34021172, 2021). "In human, alterations in KLF11 causes neonatal and juvenile Diabetes while its closely related gene, KLF14 causes obesity and adult type II diabetes." (PMID 24885560, 2014). "Similarly, KLF14 has been implicated in increasing susceptibility to type 2 diabetes by regulating key genes associated with insulin resistance." (PMID 38516000, 2024). "The study focuses on examining the relationship between a single nucleotide polymorphism (SNP) in KLF14 rs4731702 and risk of type 2 diabetes mellitus (T2DM) and dyslipidemia in different ethnic populations." (PMID 37351102, 2023). "At the KLF14 locus on chromosome 7, colocalization analyses indicated that the same genetic region likely influences both type 2 diabetes and hypertension." (PMID 41024449, 2025). "Variants in KLF14 and MOB2, which previously were shown to have parent-of-origin effects on type 2 diabetes, here showed parent-specific effects on lipid levels, with the risk-increasing allele being associated with lipid levels." (PMID 40175764, 2025). "Other genes that were assigned to lead SNPs are involved in regulating satiety and energy homeostasis (MC4R;), adiposity (LYPLAL1;), and metabolic diseases such as type 2 diabetes (KLF14;)." (PMID 38664839, 2024). "According to an investigational study, the T allele of KLF14 rs4731702 has a significant association with elevated levels of serum HDL-C, which confers protective effects against cardiac illnesses and type 2 diabetes mellitus." (PMID 37351102, 2023). "Previous studies have shown that KLF14 significantly regulates lipid metabolism and blood glucose levels, which are closely related to the pathogenesis of atherosclerosis, type 2 diabetes, insulin resistance, and other diseases." (PMID 34983946, 2022). "KLF14 is a female-specific type 2 diabetes-imprinted locus, it is only expressed from the maternally inherited allele." (PMID 32797044, 2020). "Despite reduced expression having been associated with both type 2 diabetes and certain types of cancer, further studies are needed to investigate whether type 2 diabetes predisposing alleles resulting in reduced expression of KLF14 are also associated with risk of the implicated cancers." (PMID 32705315, 2020). "Among the other potentially damaging variants, MYL5 (myosin light chain 5) p.F88S, is in a gene that is one of 10 shown to be regulated by the master trans regulator KLF14, itself associated with levels of HDL‐C and type 2 diabetes." (PMID 31617323, 2019). "In recent EWASs, around 60% of the methylation changes associated with age in pancreatic islets also occur in blood, including FHL2, KLF14, FAM123C and GNPNAT1, all genes known to be associated with type 2 diabetes or insulin secretion." (PMID 29164275, 2018). "Genetic variants at KCNQ1 rs151290, KLF14 rs972283, GCKR rs780094 and MTNR1B rs10830963 have been associated with type 2 diabetes mellitus (T2DM), but the results are contradictory in Chinese populations." (PMID 26927145, 2016).
type 2 diabetes (continued). "Variations at KLF14, the Krueppel like factor 14, were related to type 2 diabetes and HDL-cholesterol but also basal cell carcinoma in different populations." (PMID 24098730, 2013). "Findings from large-scale studies suggested a strong linkage between the genetic variants at the Krüppel-like factor 14 (KLF14) locus and serum high-density lipoprotein cholesterol (HDL-C) concentrations and type 2 diabetes." (PMID 24195066, 2013). "GWAS studies have shown that the T allele of KLF14 rs4731702 is associated with increased serum levels of HDL-C, which in turn enhances heart health and acts as a protective factor against cardiovascular diseases and type 2 diabetes mellitus." (PMID 37351102, 2023). "Of note, studies have shown that KLF14 can significantly regulate the metabolism of glucose and lipids in cases of type 2 diabetes mellitus (T2DM) and reduced insulin sensitivity." (PMID 34983946, 2022). "We also found that KLF14 was mainly enriched in pathways related to type 2 diabetes and sucrose signaling by gene set enrichment analysis (GSEA) of samples from septic patients with upregulated expression of KLF14, revealing a correlation between KLF14 and glucose metabolism pathways." (PMID 34983946, 2022).
metabolic syndrome (17 papers, 2013 to 2025). A cluster of metabolic risk factors for CARDIOVASCULAR DISEASES and TYPE 2 DIABETES MELLITUS. "A number of studies have revealed an association between KLF14 polymorphisms and methylation status, which were associated with lipid profiles, blood pressure status, insulin resistance markers, and metabolic syndrome." (PMID 40558830, 2025). "The findings revealed a trans-regulatory association between the KLF14 gene and 10 genes that have been implicated in the regulation of several metabolic disorders, including dyslipidemia, insulin resistance, and obesity." (PMID 37351102, 2023). "These single nucleotide polymorphisms in KLF14 have been associated with dyslipidemia, insulin resistance, and glucose intolerance." (PMID 36837818, 2023). "The study’s findings indicate that dyslipidemia in T2DM patients is associated with reduced KLF14 functionality due to CC and CT genotypes, leading to insulin resistance and an increased risk of cardiovascular diseases." (PMID 37351102, 2023). "KLF-14 is an important metabolic transcriptional regulator that has been implicated in metabolic syndrome." (PMID 36431040, 2022). "Studies have supported the role of KLF-14 genetic variants in induction of metabolic syndrome including obesity, insulin resistance, T2D and CVD." (PMID 36431040, 2022). "Our data indicated a significant association of KLF14 variants with various metabolic traits, such as lipid profiles, BP status, IR surrogate marker levels, and metabolic syndrome, but only in female participants." (PMID 35456983, 2022). "This has been the case for those genes within the KLF family of transcriptional regulators, such as KLF11 and KLF14, which have been strongly associated to diabetes, obesity, and insulin resistance/metabolic syndrome." (PMID 23589285, 2013). "The results suggested a trans-causal link between KLF14 expression and ten genes that were associated with a variety of metabolic syndrome traits including obesity, dyslipidemia, and measures of insulin resistance." (PMID 24195066, 2013). "It has been concluded, using large data collected from GWAS and meta-analytical studies about metabolic traits, that KLF14 has strong association with phenotypes of metabolic syndromes, including insulin resistance, LDL-C, TGs, HOMO-IR, and the waist-hip ratio." (PMID 36837818, 2023). "Moreover, SNVs in KLF-14 gene were associated with lipid profiles, status of blood pressure, resistance to insulin and metabolic syndrome." (PMID 36431040, 2022). "Our findings demonstrate that KLF14 overexpression confers protective metabolic effects in a sex‐specific manner and support the potential of KLF14‐targeted strategies for treating metabolic syndrome." (PMID 40790397, 2025). "Collectively, these findings suggest a pivotal role of KLF14 and SREBF-1 in regulating the expression of a subset of GPCRs implicated in metabolic syndrome." (PMID 40243421, 2025). "This study has investigated the association between the transcription factors KLF14 and SREBF-1 and the promoters of orphan GPCRs, aiming to elucidate their potential role in metabolic syndrome." (PMID 40243421, 2025). "Using the eukaryotic promoter database, we identified putative binding sites for the transcription factors KLF14 and SREBF-1 in the promoters of a panel of GPCRs associated with metabolic syndrome." (PMID 40243421, 2025). "Given that KLF14 and SREBF1 have been previously linked to metabolic syndrome, this observation suggests a direct connection between the regulation of these receptor expressions and the development of this condition." (PMID 40243421, 2025). "Computational analysis identified putative binding sites for KLF14 and SREBF-1 within the promoter regions of multiple GPCRs implicated in metabolic syndrome." (PMID 40243421, 2025). "KLF14 expression is affected by diet, implying its role in altered metabolic processes in metabolic syndrome." (PMID 40243421, 2025).
metabolic syndrome (continued). "In this research study, an altered lipid profile has been observed in patients with T2DM, potentially attributed to a decrease in KLF14 activity in these individuals due to dyslipidemia." (PMID 37351102, 2023). "In an investigational study, both KLF14 over-expression and down-regulation in a dyslipidemia mouse model have been studied, which concluded that hepatic-KLF14 gene deletion leads to decrease serum HDL-C levels." (PMID 36837818, 2023). "In addition to diabetes mellitus, KLF14 promoter methylation status showed a significant age-dependent association with various body shape indices and metabolic traits, and the associations with lipid profiles, HbA1c, and metabolic syndrome occurred predominantly in female participants." (PMID 35456983, 2022). "In mice, the deletion of KLF14 partially reproduces the human phenotype of insulin resistance, dyslipidemia, and T2D." (PMID 36046788, 2022). "GWAS of gene expression performed in the Multiple Tissue Human Expression Resource (MuTHER) and the Metabolic Syndrome in Men (METSIM) cohorts identified KLF14 as a master regulator of gene expression in subcutaneous adipose tissue." (PMID 32548128, 2020). "Given previous indications of metabolic syndrome-related phenotypes related to the KLF14 locus and its imprinted status, the authors reanalyzed the related network of traits, including sex-stratified analyses." (PMID 29880058, 2018). "This study aims to determine the presence of the KLF14 and SREBF-1 transcription factor binding sites in the promoters of orphan receptor genes and to be able to associate some of these orphan receptors with the development of metabolic syndrome." (PMID 40243421, 2025). "This study investigated the relationship between the transcription factors (TFs) KLF14 and SREBF-1 and orphan receptors (ORs) in the context of metabolic syndrome (MetS)." (PMID 40243421, 2025). "In conclusion, this study provides strong evidence of the importance of KLF14 and SREBF-1 in regulating orphan receptors genes and their participation in the development of metabolic syndrome." (PMID 40243421, 2025). "All this represents a high probability of incidence of these receptors with the KLF14 and SREBF-1 TFs for their possible involvement in metabolic syndrome." (PMID 40243421, 2025). "The transcription factors KLF14 and SREBF-1 are key in metabolic syndrome due to regulating lipid and glucose metabolism genes." (PMID 40243421, 2025). "While we observe an overlap in the expression of KLF14, SREBF1, and orphan receptors in tissues relevant to metabolic syndrome, specific expression patterns are also noted, which may have functional implications." (PMID 40243421, 2025). "Collectively, these tissue expression patterns lend credence to the hypothesis that KLF14 and SREBF1 can regulate the expression of orphan receptors in tissues crucial for metabolic syndrome." (PMID 40243421, 2025). "Additionally, the use of animal models is crucial to study the role of KLF14, SREBF-1, and orphan receptors in the development of metabolic syndrome in vivo." (PMID 40243421, 2025). "First, our analysis of the tissue expression patterns of KLF14, SREBF1, and orphan receptors reveals a significant overlap in tissues relevant to metabolic syndrome, suggesting a potential functional interaction between these transcription factors and the receptors." (PMID 40243421, 2025). "According to an in vivo investigation on mice, it has been found that decreased expression of KLF14 expression up-regulates the pre-adipocyte proliferation and interrupts normal lipogenesis, which results in the progression of T2DM, dyslipidemia, and insulin resistance." (PMID 36837818, 2023). "No BS for either KLF14 or SREBF1 was identified in the promoters of MC4R, 5-HT2C, MC3R, S1PR2, FFAR1/GPR40, and HCR2 within this database, despite their known association with metabolic syndrome." (PMID 40243421, 2025).
atherosclerosis (16 papers, 2018 to 2025). A disease characterized by the build-up of fatty material and calcium deposition in the arterial wall resulting in partial or complete occlusion of the arterial lumen. "The authors also identified perhexiline from a drug screen, as a KLF14 activator, and used this drug to treat ApoE-deficient mice, which have very high total cholesterol levels and develop atherosclerosis." (PMID 32548128, 2020). "Given that aberrant nutrient handling, obesity, and type 2 diabetes are risk factors for atherosclerosis, it is unsurprising that multiple genetic variants involving the KLF14 gene have been implicated in the development of atherosclerotic disease." (PMID 29459900, 2018). "Genome-wide association studies during the last few years have linked the Krüpple-like family of transcription factors such as KLF14, which contribute to the mechanisms of mammalian gene regulation, with certain altered metabolic traits and risk of atherosclerosis and type-2 DM." (PMID 35455702, 2022). "Genome-wide association studies during the last few years have also linked the Krüpple-like family of transcription factors such as KLF14, which contribute in mechanisms of mammalian gene regulation, with certain altered metabolic traits and risk of atherosclerosis and type-2 DM." (PMID 35455702, 2022). "How KLF14 regulates these metabolic traits and increases the risk of developing T2D, atherosclerosis, and liver dysfunction is still unknown." (PMID 32548128, 2020). "Together, this work provides evidence that KLF14 may play a causal role in modulating inflammation associated with atherosclerosis, further implicating it in metabolic disease." (PMID 29459900, 2018). "Perhexiline regulates the KLF14 pathway, and the results revealed that this intervention diminishes the development of atherosclerotic lesions in the apolipoprotein E-deficient mice which have a high cholesterol level and more chances for the development of atherosclerosis." (PMID 36837818, 2023). "In summary, KLF14 exerts multi-target protective effects in atherosclerosis, while its antagonistic effects with family members such as KLF5 reveal the complexity and therapeutic potential of the KLF network regulation." (PMID 41373858, 2025). "The apolipoprotein E-deficient mice have a high cholesterol level and high chances for the development of atherosclerosis, whereas perhexiline decreases systemic cholesterol levels via activation of the KLF14 pathway." (PMID 36837818, 2023). "Recent studies have shown that KLF14 plays a protective role against multiple aging‐related diseases, including type 2 diabetes, atherosclerosis, and AD." (PMID 37551728, 2023). "Perhexiline is an activator of KLF14 expression, used as a prophylactic anti-anginal agent, which increases HDL-C levels and represses the risk of atherosclerosis." (PMID 36837818, 2023). "Several lines of evidence suggest that KLF14 is a protective gene against atherosclerosis and diabetes via mediating lipid signaling and glucose metabolism." (PMID 37551728, 2023). "Previous studies have found that perhexiline can reduce the formation of atherosclerosis through the activation of KLF14 expression, and this strategy is currently used in the clinical treatment of cardiovascular diseases." (PMID 37551728, 2023). "Previous studies have found that perhexiline can reduce the formation of atherosclerosis through activation of KLF14 expression, and this strategy is currently used in clinical cardiovascular-related diseases." (PMID 34983946, 2022). "Administration of perhexiline increased hepatic KLF14 expression and HDL-C plasma levels which has a protective effect against atherosclerosis in ApoE-deficient mice." (PMID 32548128, 2020). "Thus, the up-regulation of hepatic KLF14 expression imparts protective effects against atherosclerosis." (PMID 36837818, 2023).